CRABP1 (cellular retinoic acid binding protein 1)
Diseases named in the same sentence as CRABP1 in open-access papers (continued):
Sharing a sentence is not in itself a finding about the gene and the disease.
melanoma (1 paper, 2021). A malignant, usually aggressive tumor composed of atypical, neoplastic melanocytes. "Eleven genes were significantly differentially expressed between metastases and primary tumors, and ALB, ORM2, CRABP1, and APOH may be associated with the metastasis of melanoma." (PMID 34154655, 2021). "There is no relevant functional study on the relationship between ALB, ORM2, CRABP1, and APOH and melanoma metastasis, which may represent future candidates." (PMID 34154655, 2021).
mesenchymal tumors (1 paper, 2015). "Among the differentially expressed genes, cellular retinoic acid binding protein 1 (CRABP1) primarily caught our attention, because of the highest fold increase upon knock-down of CIC in PC-3 cells and its previously known pro-tumorigenic and pro-metastatic activity in mesenchymal tumors." (PMID 26124181, 2015).
motor neuron degeneration (1 paper, 2020). "As introduced earlier, recent expression data have shown that CRABP1 level is lower in conditions of motor neuron degeneration such as ALS and SMA." (PMID 32527063, 2020).
neuroendocrine tumors (1 paper, 2020). "CRABP1 has a pro-tumorigenic and a pro-metastatic activity in mesenchymal and neuroendocrine tumors." (PMID 32041153, 2020).
oral squamous cell carcinoma (1 paper, 2019). "Furthermore, CRABP1 together with β-catenin was expressed in sebaceous gland tumours, and CRABP1 as part of retinoic acid signalling enhanced malignancy of human mesenchymal cells and invasiveness of oral squamous cell carcinoma in vitro." (PMID 31065284, 2019).
Primary hypothyroidism (1 paper, 2024). A type of hypothyroidism that results from a defect in the thyroid gland. "As introduced earlier, this study was prompted by our surprising finding of mature thyrocyte malfunction caused by the disruption of Crabp1 gene, because CKO mice developed adult-onset primary hypothyroidism with apparent defected thyrocytes, but the mechanism remains unknown." (PMID 39594593, 2024).
spinal muscular atrophy (1 paper, 2020). A motor neuron disease that affect the muscles, and characterized by muscle weakness and atrophy resulting from progressive degeneration and irreversible loss of the anterior horn cells in the spinal cord (i.e., lower motor neurons) and the brain stem nuclei. "Expression data mining of ALS and spinal muscular atrophy (SMA) motor neurons shows reduced CRABP1, coincided with reduction in Shh-Gli1 signaling components." (PMID 32527063, 2020). "As human gene expression data have become increasingly available, it is interesting to recognize that CRABP1 expression is down-regulated in motor neurons of proximal spinal muscular atrophy (SMA) cells and animal models." (PMID 32527063, 2020).
triple-negative breast carcinoma (1 paper, 2015). An invasive breast carcinoma which is negative for expression of estrogen receptor (ER), progesterone receptor (PR), and human epidermal growth factor receptor 2 (HER2). "We propose that these three RA-binding proteins can serve as biomarkers for predicting triple-negative breast cancer response to RA, with elevated levels of either cytoplasmic CRABP1 or FABP5 associated with RA resistance, and elevated levels of nuclear CRABP2 associated with sensitivity to RA." (PMID 26142905, 2015). "Like FABP5, CRABP1 is preferentially expressed in ER- and triple-negative breast cancer." (PMID 26142905, 2015). "We then co-transfected two triple-negative breast cancer cell lines (Hs-578 T and BT-549) and one ER-negative/HER2 overexpressing cell line (SK-Br-3) with a CRABP1 expression construct and the RARE-luciferase reporter vector." (PMID 26142905, 2015).
tumor (37 papers, 2004 to 2025). "Similar to CRBPs, CRABP1 has been implicated in tumour suppression, with studies showing that its mRNA levels are reduced in certain human epithelial tumours (colorectal and hepatocellular cancers) due to hypermethylation of its promoter region." (PMID 41149452, 2025). "Nevertheless, given the conservation of CRABP1 across mammals, any alterations in CRABP1 caused by these SNPs could potentially disturb CRABP1 functions and normal cellular processes especially proliferation which could impact tumor formation or progression." (PMID 35406141, 2022). "CRABP1, which is a member of a family of small cytosolic lipid binding proteins and encodes a cellular retinoic acid binding protein, was the only gene in which hypermethylation was found and then only in two clear cell tumours." (PMID 17623056, 2007). "Clustering analysis of tumor cells revealed six subclusters exhibiting transcriptional heterogeneity, including Cp+, Cldn5+, Crabp1+, Ebf1+, Ptprc+, and Srgn+ tumor cells." (PMID 39979981, 2025). "Despite heterogeneity in tumor mass within each group, substantial growth differences occurred when Crabp1, Mif, and Sox9 were targeted, highlighting their role in tumor growth." (PMID 41223283, 2025). "CRABP1 expression appears to be reduced in many the cancer types, suggesting a tumour suppressor role, although it acts as tumour promoter in others." (PMID 41149452, 2025). "We determined genes that correlate with CRABP1 expression in bulk expression to find that the HOX genes were among the strongest correlates in both tumor datasets." (PMID 36759899, 2023). "Given its notable expression pattern in the single-cell tumor datasets, we examined CRABP1 expression in the developing hindbrain utilizing a scRNA-seq dataset generated from human brain samples from the first trimester." (PMID 36759899, 2023). "Expression of cellular retinoic acid binding protein 1 (CRABP1) was a clear outlier for both tumor subtypes." (PMID 36759899, 2023). "Specifically, we observed the presence of copy number variants (CNVs) in 5q and 20q in addition to DEGs, such as COL9A3 and CRABP1, shared with other putative tumor clusters described further below." (PMID 35534852, 2022). "Specifically, CRABP1, which proved to be under-expressed in hormone-dependent tumours but maintained at high expression levels in triple-negative tumours, inhibits retinoic acid which should normally inhibit growth and induce apoptosis." (PMID 36536459, 2022). "For instance, the CRABP1 gene has been reported as a tumor suppressor or an oncogene in animals and humans." (PMID 35406141, 2022). "The effect of Crabp1 on ERK pathway is elicited mainly in proliferating cells such as tumor or stem cells, whereas that on CaMKII pathway is elicited mainly in differentiated cells such as cardiomyocyte and neurons." (PMID 34830120, 2021). "The expression of CRABP1 was found in the IM in the early superficial BCCs as well as in the TSI and IIF of more aggressive BCC including sclerosing and infiltrative types where up to 88% of tumour stroma was positive for CRABP1." (PMID 31065284, 2019). "Both cytoplasmic and nuclear CRABP1 immunoreactivities were positively correlated with triple-negative status and high histological tumor grade." (PMID 26142905, 2015). "High CRABP1 mRNA levels correlated with positive nodal status (p = 0.021), high nuclear grade (p < 0.0001), mitotic grade (p < 0.0001) and overall histological tumor grade (p < 0.0001)." (PMID 26142905, 2015). "In summary, we show that CRABP1 expression is maintained in ER- and triple-negative breast tumors, and that elevated levels of CRABP1 is a significant indicator of high tumor grade, Ki67 immunoreactivity, and poor prognosis." (PMID 26142905, 2015). "The transcription factor AP-2α (TFAP2A), a RA-inducible gene with tumor-suppressing activity, was upregulated by CRABP1 depletion and RA treatment at a dose up to 5 nM." (PMID 26142905, 2015).
tumor (continued). "In particular, CRABP1 was expressed in the tumor stroma, and CRABP2 and FABP5 were expressed in the sebaceous gland cells, interfollicular epidermis, and hair follicles." (PMID 26503156, 2015). "DNA hypermethylation of tumour suppressor genes seems to play an important role in ovarian carcinogenesis and HOXA9, HOXB5, SCGB3A1, and CRABP1 are identified as novel hypermethylated target genes in this tumour type." (PMID 17623056, 2007). "Moreover, retinoic acid and cellular retinoic acid-binding protein 1 (CRABP1) are involved in the regulation of gene expression, which can inhibit tumor formation." (PMID 37895197, 2023). "Overall, these data support a role for CRABP1 in specific tumor cell-states in both tumors, consistent with the hypothesis that PFA and DMG tumors may benefit from expression of similar genes to maintain progenitor states." (PMID 36759899, 2023). "This supports the notion that CRABP1 can be a tumor suppressor." (PMID 35406141, 2022). "Maprotiline can directly bind to CRABP1 and inhibit its biological activity, which possibly suppress the phosphorylation of SREBP2 caused by ERK pathway activation and finally inhibit cholesterol biosynthesis and tumor growth." (PMID 34093212, 2021). "In this study, we addressed the question whether different regulators of the dermal compartment such as CRABP1, Nestin, and Ephrin B2 are markers preserved directly in the surrounding tumour stroma of skin appendages tumours." (PMID 31065284, 2019). "Since we used Herovici's collagen stain to allocate CRABP1-positive cells in the tumour stroma and the preexisting dermis, we could verify that CRABP1-positive cells are located in the tumour stroma and located in the environment of tumour cells." (PMID 31065284, 2019). "The role of CRABP1 in carcinogenesis and tumor progression is poorly understood and contradictory." (PMID 26142905, 2015). "Interestingly, some of these genes have been previously associated with CIMP in other tumor types, such as p73, GSTP1, SOCS-1, CACNA1G, CRABP1, NEUROG1 and RUNX3." (PMID 20830311, 2010). "We found significant associations between CRABP1 immunoreactivity and poor prognosis (Fisher’s exact test, p = 0.006 for grade and p = 0.008 for survival status); however, we did not observe any significant difference in tumor stage (Fisher’s exact test, p = 0.205)." (PMID 35069566, 2021). "In addition, metastatic tumor cells also specifically expressed some genes, such as DPPA3, NANOG, CRABP1 and others." (PMID 35494058, 2022). "Similarly to FABP5, CRABP1 is also preferentially expressed in ER- and TNBC tumor tissues that are prone to ATRA resistance." (PMID 30384831, 2018). "The non-genomic activity of atRA/Crabp1 affects PP2A and modulates cell cycle progression in ESC, which supports genetic association studies suggesting Crabp1 as a tumor suppressor." (PMID 26935534, 2016). "This current study reveals a mechanism in which Crabp1 can play a role as a tumor suppressor, through non-canonical activation of ERK1/2 that then induces apoptotic pathways, likely through inhibiting anti-apoptosis, for cancer cell death." (PMID 26935534, 2016). "In our data, the CRABP1 protein was not expressed strongly in the tumor cells of SeCC cases, whereas the CRABP2 protein was overexpressed in the tumor cells of SeCC cases." (PMID 26503156, 2015). "There were no studies of ANGPTL4, CRABP1, MET, and SEMA3A in Oncomine, but in UALCAN, they were frequently expressed in tumor group than normal tissues." (PMID 35833114, 2022).
cancer (35 papers, 2007 to 2025). A tumor composed of atypical neoplastic, often pleomorphic cells that invade other tissues. "Gene expression data and CRABP1 gene single nucleotide polymorphisms (SNPs) of human cancer, neurodegeneration, and immune disease patients implicate the potential association of abnormality in CRABP1 with human diseases." (PMID 35406141, 2022). "In comparing CKO and wild-type ESCs, as well as in gain- and loss-of-functional studies of cancer cell models, it was found that CRABP1 was involved in modulating cell cycle control." (PMID 35406141, 2022). "CRABP1 belongs to a family of fatty acid-binding proteins and is associated with a poor prognosis in several cancers." (PMID 34201893, 2021). "C3 and C4 were initially found to target the CRABP1–MAPK signalosome to induce cancer-cell apoptosis." (PMID 41154657, 2025). "Cells in cluster 5 resembled those in cluster 7 of DNs, and included cells with aberrant neuronal identity that expressed neuronal genes (GAP43, NEFM, DCX, HES6) and cancer-related proliferative genes (CRABP1, MYC, SFRP1)." (PMID 33771987, 2021). "Subsequently, we aimed to verify the cancer-promoting effect of CRABP1 at the cellular level, so we constructed CRABP1-overexpressing cell lines." (PMID 34093212, 2021). "Given that CRABP1 can intercept growth factor signaling, can CRABP1 also serve as a target in cancer therapy?" (PMID 31344789, 2019). "As a proof of concept, we examine these compounds, through binding to Crabp1, in enhancing Crabp1-positive cancer cell apoptosis." (PMID 26935534, 2016). "For a proof-of-concept, the current study further demonstrates a strategy using these compounds to enhance apoptosis specifically in Crabp1-positive cancer cells." (PMID 26935534, 2016). "The ability of holo-Crabp1 to increase the Bax/Bcl-2 ratio also suggests a potential to sensitize resistant cancer cells to current therapies." (PMID 26935534, 2016). "Based on our gene profiling data, CRABP1 is markedly down-regulated in ER-positive breast tumors in keeping with reports indicating that CRABP1 is silenced in cancer cells." (PMID 26142905, 2015). "For example, CRABP1 is down-regulated in some human cancers and cell lines, with DNA methylation proposed to contribute to CRABP1 silencing." (PMID 26142905, 2015). "Overall, gene methylation frequencies were higher among MSI than among MSS carcinomas, and were statistically significant for CRABP1, MLH1, NR3C1, RUNX3, and SCGB3A1 (P ≤ 0.0001, P ≤ 0.0001, P = 0.001, P ≤ 0.0001, and P = 0.03, respectively)." (PMID 19117505, 2008). "Our data support the view that promoter hypermethylation is a common mechanism involved in ovarian carcinogenesis and four target genes, HOXA9, HOXB5, SCGB3A1, and CRABP1, novel to this cancer type are identified." (PMID 17623056, 2007). "Importantly, human studies have also shown drastically altered expression of CRABP1 in various diseases such as neurodegeneration, autoimmune diseases, and cancers, supporting human disease relevance of the CKO phenotypes." (PMID 39075476, 2024). "Nevertheless, these ligands could elicit CRABP1-dependent biological effects in cultured cell models of cancers and MN degeneration." (PMID 37822422, 2023). "Dysregulation of CRABP1 expression in cancers is a well-documented phenomenon." (PMID 35406141, 2022). "For example, the expression of CRABP1 of cancers from various origins are significantly different." (PMID 36419120, 2022). "The role of CRABP1 in tumorigenesis is relatively unknown, with reports of both up- and downregulation in different cancer types." (PMID 35069566, 2021). "Serum methylated SST was significantly associated with cancer-specific survival among all other detected markers tested in the same study (TAC1, MAL, SEPT9, NELL1, CRABP1, EYA4, and CEA) at the preoperative time point, while its methylation status after operation had no value on prognosis." (PMID 30944663, 2019).
cancer (continued). "In fact, knock-down of CIC more dramatically increased cell proliferation and invasion in PC-3 cells than overexpression of CRABP1, suggesting that not only CRABP1, but other genes regulated by CIC are also involved in promotion of cancer progression by CIC deficiency." (PMID 26124181, 2015). "The expression of aldehyde hydrogenase ALDH1B1 gene, which is involved in RA biosynthesis and associated with cancer cell stemness, was induced by RA in the control cells but not in the CRABP1-depleted cells." (PMID 26142905, 2015). "ChIP experiments show that the Sp1 occupies its binding sites in the promoters of XIAP, CRABP1, MDK, and KCNMA1, and that DIG-MSK decreases Sp1 binding to them with a superior effect on KCNMA1, a gene associated with high proliferation in cancer cells." (PMID 25110883, 2014). "Finally, from a therapeutic point of view, compounds specific to CRABP1 that do not bind to RARs/RXRs would be better candidates as therapeutics for targeting CRABP1 to selectively intercept certain biological processes, such as inhibiting cancer cell growth and improving survival/function." (PMID 31344789, 2019). "For example, AKR1B15, COL17A1, CRABP1, and ITPRID1 were downregulated in BRCA, COAD, and PRAD but upregulated in LUAD, highlighting their cancer type-specific regulatory behavior." (PMID 41439026, 2025). "Analysis of cluster-specific genes indicates that these clusters correspond to cancer cells (GFP, Crabp1, Ank), myeloid cells (Aif1, Ctsc, Mpeg1), lymphoid cells (Il2rb, Cd28, Cd3e/g/d, Cd37), and stromal cells (Col1a1/2, Lum, Eln, Dpt), respectively." (PMID 41280683, 2025). "We first discuss the role of CRABP1 in regulating MAPK activities and its implication in stem cell proliferation, cancers, adipocyte health, and neuro-immune regulation." (PMID 35406141, 2022). "CRABP1, CRABP2, CYP and RAR expressions can be upregulated or downregulated depending on the cancer type and administrated anticancer drugs." (PMID 30322383, 2018). "While increased CRABP2 expression has been observed in AB1 embryonic stem cells with homozygous deletion of CRABP1, this is the first report demonstrating that CRABP1 has an inhibitory effect on CRABP2 expression in cancer cells." (PMID 26142905, 2015). "Hypermethylated CRABP1, MLH1, NR3C1, RUNX3, and SCGB3A1 were shown to be identifiers of carcinomas with microsatellite instability." (PMID 19117505, 2008). "Specifically, without growth-factor-activated Ras, these compounds could bind CRABP1 to activate ERK1/2 to target protein phosphatase 2 (PP2A), ultimately inducing apoptosis in cancer cells." (PMID 41154657, 2025). "Although CRABP1 has been shown to promote cancer progression independent of the retinoid acid binding activity, the mechanisms underlying the aggressiveness of CRABP1 in EC remain to be determined." (PMID 35069566, 2021). "By using Crabp1-selective compounds, it is possible to dampen growth signal in certain cancers without eliciting RAR-mediated retinoid toxicity." (PMID 31358819, 2019). "In conclusion, we found that expression of the individual genes CRABP1 and LCN2 may be useful biomarkers in DTC, able to improve FNAB differential diagnosis of benign versus malignant tumours." (PMID 29321030, 2018). "Re-expressing Crabp1 in Crabp1-negative cancer cells also sensitizes their apoptotic induction by atRA." (PMID 26935534, 2016). "On the other hand, it has also been reported that the cancer promoting activity of CRABP1 is independent of the retinoic acid binding activity." (PMID 26124181, 2015). "Only carcinomas showed significantly elevated hypermethylation frequencies for MLH1 and CRABP1." (PMID 26203307, 2015). "The CRABP1 protein was differentially expressed between the FTA samples compared to the PTC and FTC samples, with a decreased expression of both RNA and protein in the malignant tumors." (PMID 19893615, 2009).
cancer (continued). "The first consists of CRABP1 and its direct interaction partner, Raf-1 kinase; formation of CRABP1-Raf-1 signalosome dampens Ras-triggered mitogen-activated protein kinase (MAPK) pathway activation, and ultimately modulates various normal cellular processes and cancer cell apoptosis." (PMID 39075476, 2024). "Finally, methylation of CRABP1, MLH1, NR3C1, RUNX3, and SCGB3A1 were identifiers of MSI carcinomas." (PMID 19117505, 2008). "Crabp1-negative cells may reflect either the lack of expression in certain cell populations that give rise to these cancer cells, or epigenetic changes of the original cells that give rise to these cancer cells." (PMID 26935534, 2016). "However, the fact that RA metabolites can activate RAR in vitro, combined with the observation that a positive relationship exists between RA metabolism and cell growth inhibition in several cancer cell lines, suggest that CRABP1-mediated RA metabolism may not account for RA resistance." (PMID 26142905, 2015).